AIM2 (absent in melanoma 2)
Diseases named in the same sentence as AIM2 in open-access papers (continued):
Sharing a sentence is not in itself a finding about the gene and the disease.
osteoarthritis (3 papers, 2020 to 2022). A noninflammatory degenerative joint disease occurring chiefly in older persons, characterized by degeneration of the articular cartilage, hypertrophy of bone at the margins and changes in the synovial membrane. "More importantly, it was reported that AIM2 was increased in RA synovium compared to osteoarthritis (OA) patients." (PMID 36120327, 2022). "AIM2 levels were higher in FLSs of RA patients than those in osteoarthritis (OA), and FLS proliferation was inhibited by silencing AIM2 in FLSs." (PMID 35095918, 2021).
pancreatic cancer (3 papers, 2020 to 2025). "In a pancreatic cancer mouse model, deficiency of Pink1 and Park2 accelerated pancreatic tumorigenesis through mitochondrial iron accumulation and AIM2 inflammasome activation in tumor cells." (PMID 32630319, 2020). "In addition, a low level of PARK2, but increased AIM2 expression, has been associated with a poor prognosis in pancreatic cancer patients." (PMID 32630319, 2020). "In summary, RP-6306 not only facilitates GSDMD cleavage but also robustly activates a network of upstream signaling pathways including NLRP3, AIM2, and Caspase-1 in pancreatic cancer cells." (PMID 40664640, 2025). "CNV-positive cells expressed Krt20, a marker of pancreatic cancer cells, and Aim2, which activates caspase 1 to process Il1 and Il18 precursors and regulates inflammasome activation." (PMID 32908137, 2020).
pancreatitis (3 papers, 2019 to 2025). Inflammation of the pancreas. "Furthermore, the authors discovered that under these conditions, L-arginine-induced pancreatitis is less common in AIM2- and RAGE-deficient animals, and HMGB1 expression an inflammasome products is also less common." (PMID 40150718, 2025). "The AIM2 inflammasome, which is lacking in melanoma 2, has been linked to a DAMP–PRR interaction in pancreatitis, according to recent reports." (PMID 40150718, 2025).
Peri-Implantitis (3 papers, 2024 to 2025). An inflammatory process with loss of supporting bone in the tissues surrounding functioning DENTAL IMPLANTS. "A cross-sectional study showed that inflammasomes (AIM2, NLRP3), and their downstream effectors (interleukin-1β, caspase-1), are strongly associated with specific bacteria in peri-implantitis." (PMID 40851867, 2025). "In fact, if we consider the network analysis, it can be suggested that in peri-implantitis, NLRP3 plays a more relevant role compared with AIM2." (PMID 38256037, 2024). "Only a recent study by our group has demonstrated that both the inflammasomes AIM2 and NLRP3 are highly expressed in peri-implantitis lesions from human patients and correlate with other markers of inflammation, tissue destruction, and clinical variables such as PD." (PMID 38256037, 2024). "In peri-implantitis, LPS + Ti strongly activates NLRP3, but without AIM2 activation, IL-1β and pyroptosis remain lower than in WT cells." (PMID 40490723, 2025).
pulmonary tuberculosis (3 papers, 2021 to 2024). A bacterial infection that affects the lungs and is caused by Mycobacterium tuberculosis. "Genetic models of association SNV rs1103577 of AIM2 gene adjusted for sex and age in patients with pulmonary tuberculosis (PTB) and healthy control." (PMID 33868225, 2021). "AIM2 detects intracellular DNA, facilitating the release of pro-inflammatory cytokines IL-18 and IL-1β, which have been associated with protection against pulmonary tuberculosis (PTB)." (PMID 38935691, 2024).
radiation pneumonitis (3 papers, 2021 to 2024). Inflammation of the lung due to harmful effects of ionizing or non-ionizing radiation. "Recently, andrographolide has been shown to also inhibit the AIM2 inflammasome by preventing AIM2 from translocating into the nucleus to sense DNA damage during the development of radiation fibrosis in BMDM cells." (PMID 35754962, 2022). "In a rat model of radiation pneumonitis (RP), radiotherapy increased the mRNA expression level of AIM2, which further triggered the release of IL-1β and induced RP, suggesting that the activation of the AIM2 inflammasome by radiotherapy may contribute to the pathogenesis of RP." (PMID 35004305, 2021).
schistosomiasis (3 papers, 2020 to 2025). An infectious disease caused by parasitic trematodes of the genus Schistosoma that colonize human blood vessels and release eggs that can cause granulomatous reactions leading to acute (swimmer's itch or acute schistosomiasis syndrome) or chronic disease. "Our findings establish NLRP3/AIM2-Gsdmd axis as a central inducer of pathogenic Th17 responses which is counteracted by IFN-I pathway in schistosomiasis." (PMID 38559160, 2024). "Similarly, AIM2 seems to be upregulated during schistosomiasis, another parasitic infection strongly associated with liver fibrosis." (PMID 32906750, 2020). "However, whether AIM2 activation contributes to liver fibrosis during schistosomiasis still needs to be demonstrated." (PMID 32906750, 2020). "Pretreatment of NLRP3-/- and AIM2-/- BMDCs with IFN-I receptor blocking antibody led to a marked increase in IL-1β and IL-17 production, demonstrating a novel mechanism by which IFN-I signaling regulates inflammation in schistosomiasis." (PMID 40100932, 2025).
tuberculosis (3 papers, 2021 to 2023). A chronic, recurrent infection caused by the bacterium Mycobacterium tuberculosis. "A meta-analysis performed with 16 microarray datasets to profile the host transcriptional response in active tuberculosis led to the identification of five upregulated genes: AIM2, BATF2, FCGR1B, HP, and TLR5." (PMID 35456421, 2022). "In this context, we have focus on one SNV in the AIM2 inflammasome in tuberculosis together with two other SNVs, one in CARD8 and one in CTSB, that are related to NLRP3 pathway." (PMID 33868225, 2021).
vascular dementia (3 papers, 2023 to 2025). A degenerative vascular disorder affecting the brain. "Here, guided by clinical patient data and computational modeling, we developed an AIM2 inflammasome-targeting biomimetic mineralization inhibitor for vascular dementia (VaD) therapy." (PMID 40521199, 2025).
abdominal aortic aneurysm (2 papers, 2023 to 2025). Enlargement and ballooning of the vessel that supplies arterial blood to the abdomen, pelvis and legs. "Increased AIM2-inflammasome activity in the aortic wall is associated with abdominal aortic aneurysm (AAA)." (PMID 40542152, 2025). "Researchers also found that various proinflammatory factors in patients with abdominal aortic aneurysms cause an imbalance of CD4+ T cells and upregulate the expression of AIM2 in them." (PMID 36742336, 2023).
abscess (2 papers, 2017 to 2022). An inflammatory process characterized by the accumulation of pus within a newly formed tissue cavity which is the result of a bacterial, fungal, or parasitic infection or the presence of a foreign body. "Consistently, the mutant strain caused sizeable abscess lesions compared to wild-type strain in wild-type mice, and AIM2 deficiency significantly reduced the impact of the mutant strain." (PMID 36128739, 2022).
acute pancreatitis (2 papers, 2019 to 2025). An acute inflammatory process that leads to necrosis of the pancreatic parenchyma. "We previously demonstrated that AGER contributes to AIM2 inflammasome activation by modulating dsRNA-dependent protein kinase phosphorylation in macrophages during acute pancreatitis." (PMID 31440260, 2019).
ankylosing spondylitis (2 papers, 2025 to 2026). An autoimmune chronic inflammatory disorder characterized by inflammation in the vertebral joints of the spine and sacroiliac joints. "In this review, we provide an overview of the available data regarding the role of the AIM2 inflammasome in chronic autoimmune and autoinflammatory diseases, with emphasis on its contribution to the pathophysiology of ankylosing spondylitis (AS) and its potential as a therapeutic target." (PMID 41369412, 2025).
autoimmune thyroiditis (2 papers, 2018 to 2021). "A study explored the link between inflammasomes and autoimmune thyroiditis, and revealed the activation of NLRP1, NLRC4, and AIM2 inflammasomes in the thyroid tissues from patients with AIT." (PMID 34234669, 2021). "Correlation between NLRP3, NLRP1, NLRC4, absent in melanoma 2 (AIM2), ASC, caspase-1, IL-1β, and IL-18 expression in the autoimmune thyroiditis group." (PMID 29915579, 2018).
C-hepatitis (2 papers, 2021 to 2022). "Purinergic receptors have been associated with HCV; thus, P2X4R regulates the secretion of micro-RNA containing exosomes by HCV-infected hepatocytes, and polymorphisms of genes encoding for inflammasome components, including AIM2, have been correlated to the development of C-hepatitis in Amazonia." (PMID 36294318, 2022). "In the present study, we analyzed whether polymorphisms in inflammasomes genes IL1B rs16944, IL18 rs187238, NLRP3 rs10754558, CARD8 rs2009373, CTSB rs1692816 and AIM2 rs1103577 are associated with susceptibility to HCV infection and liver fibrosis in hepatitis C patients in the Amazon population." (PMID 34161370, 2021). "Similarly, heterozygote carriers for CTSB rs1692816 and AIM2 rs1103577 (padj = 0.008) or for IL18 rs187238 and NLRP3 rs10754558 (padj = 0.005), have less chances to the development of hepatitis C." (PMID 34161370, 2021).
central nervous system infection (2 papers, 2020 to 2024). "Regarding AIM2, studies have shown that AIM2 inflammasome-mediated neuronal apoptosis is an essential cell death mechanism in the central nervous system infection and damage." (PMID 32377306, 2020).
chronic viral hepatitis (2 papers, 2020 to 2022). "P2X7R and P2X4R play a major role in liver inflammation accompanying chronic HCV infection, especially when combined with metabolic damage, while AIM2 is specifically expressed in chronic viral hepatitis." (PMID 35806450, 2022). "In conclusion, both P2X7R and P2X4R seem to play a role in liver inflammation accompanying chronic HCV infection, especially when combined with metabolic damage, while AIM2 appears specifically expressed in chronic viral hepatitis." (PMID 35806450, 2022).
Cirrhosis (2 papers, 2020 to 2025). A chronic disorder of the liver in which liver tissue becomes scarred and is partially replaced by regenerative nodules and fibrotic tissue resulting in loss of liver function. "Similarly, it would be interesting to address the role of AIM2 during acute-on-chronic liver failure, a different syndrome characterized by acute and severe liver abnormalities in patients with underlying chronic liver disease or cirrhosis." (PMID 32906750, 2020). "While the inflammasome‐dependent function of AIM2 in hepatocytes and macrophages in the liver may be harmful in conditions such as steatohepatitis, liver injury, and cirrhosis, AIM2 confers protection against drug‐induced hepatoxicity." (PMID 39158380, 2025). "In addition, AIM2 activation correlated with the severity of cirrhosis, because ascitic fluid macrophages from patients with more severe disease produced higher amounts of IL-1β and IL-18 in response to dsDNA." (PMID 32906750, 2020).
co-infection (2 papers, 2022 to 2023). "To test whether the effect of HBV inducing AIM2 in vitro occurs really in HBV/HCV mono- and co-infection, we compared AIM2 expression of monocytes among HBV/HCV mono- and co-infected patients and HD." (PMID 37787533, 2023). "The mRNA expression level of AIM2 was positively correlated with HBV viral load in HBV mono-infection and HBV/HCV co-infection, but not with HCV viral load in HCV mono-infection and HBV/HCV co-infection." (PMID 37787533, 2023).
dilated cardiomyopathy (2 papers, 2022 to 2025). Cardiomyopathy which is characterized by dilation and contractile dysfunction of the left and right ventricles. "During myocardial inflammation and dilated cardiomyopathy due to depletion of carnitine acetyltransferase (CRAT), type I IFN responses increase AIM2 expression and AIM2 inflammasome activation in cardiomyocytes." (PMID 39158380, 2025).
encephalomyelitis (2 papers, 2017 to 2024). Inflammation of the brain and the spinal cord. "AIM2 and viral antigens were detected by immunohistochemistry in infected neurons in inflamed areas of the CNS in EV-A71 encephalomyelitis." (PMID 28724943, 2017). "In agreement with AIM2 up-regulation in infected SK-N-SH cells, AIM2 protein was detected in neurons and inflammatory cells in human EV-A71 encephalomyelitis." (PMID 28724943, 2017). "AIM2 expression in human CNS tissues of EV-A71 encephalomyelitis was also demonstrated." (PMID 28724943, 2017). "This suggests that AIM2 inflammasome-mediated pyroptosis may play an important role in limiting EV-A71 replication in general as both mild HFMD and fatal encephalomyelitis viral isolates could infect neuronal cells and up-regulate AIM2 expression." (PMID 28724943, 2017).
endometriosis (2 papers, 2018 to 2023). The growth of functional endometrial tissue in anatomic sites outside the uterine body. "Absent in melanoma 2 (AIM2)-like receptors (ALRs) and retinoic acid-inducible gene I-like receptors (RLRs) may be involved in the activation of endometriosis-associated immune and inflammation disorders." (PMID 37033937, 2023).
head and neck squamous cell carcinoma (2 papers, 2022 to 2024). A squamous cell carcinoma that arises from any of the following anatomic sites: lip and oral cavity, nasal cavity, paranasal sinuses, pharynx, larynx, and salivary glands. "We dissected the transcriptional profile of AIM2 in the normal tissues and primary tumors derived from head and neck squamous cell carcinoma (HNSCC) patients in The Cancer Genome Atlas (TCGA) database." (PMID 38166970, 2024). "AIM2 had significantly higher expression in DLBC, LAML, LUAD, LUSC, and PRAD and lower in BLCA, BRCA, CESC, COAD, ESCA, GBM, Head and Neck squamous cell carcinoma (HNSC), KIRC, LGG, OV, PAAD, SKCM, STAD, and THYM (all P < 0.05)." (PMID 36248785, 2022).
intracerebral hemorrhage (2 papers, 2025). A cerebrovascular disorder characterized by bleeding into one or both cerebral hemispheres including the basal ganglia and the cerebral cortex. "Our study demonstrates that AMG487-mediated inhibition of CXCR3 maintains blood–brain barrier integrity and enhances both short-term and long-term neurological deficits after intracerebral hemorrhage by suppressing the cGAS-STING/AIM2 signaling pathway in mice." (PMID 40781073, 2025).
kidney inflammation (2 papers, 2012 to 2022). "A previous study reported that pristane-injected Aim2-/- mice developed less kidney inflammation, autoantibody production, and proteinuria." (PMID 36591278, 2022).
Listeria infection (2 papers, 2017). "In addition, dsDNA transfection and Listeria monocytogenes infection were utilized to activate AIM2 inflammasome in LPS-primed macrophages." (PMID 28963531, 2017).
Liver Fibrosis (2 papers, 2019 to 2020). "However, much more research is needed to better explain the function of AIM2 during liver fibrosis." (PMID 32906750, 2020). "Finally, to verify the in vivo significance of our hypothesis, Casp-1, ASC, NLRP3, and AIM2 KO mice and WT mice, as control, were infected with B. abortus, and 4 weeks later, animals were sacrificed to determine the role of inflammasome in the liver fibrosis." (PMID 32038610, 2019).
myocarditis (2 papers, 2017 to 2021). Myocarditis is a condition that is characterized by inflammation of the heart muscle (myocardium). "Our results indicate that AIM2-adjuvanted vaccine could be a potential and promising approach to promote a long-lasting protection against CVB3-induced myocarditis." (PMID 28642849, 2017).
on-small cell lung cancer (2 papers, 2020 to 2023). "For instance, NSCLC shows overexpressed AIM2, while lung adenocarcinoma and small cell lung cancer (SCLC) show upregulated NLRP3." (PMID 36932407, 2023). "AIM2 protein levels were reported to be frequently overexpressed in several types of malignancies including OSCC and on-small cell lung cancer, and its overexpression promoted cancer progression and predicted poor survival of patients." (PMID 33291082, 2020).
oral disease (2 papers, 2020 to 2025). "How the AIM2 inflammasome is related to oral diseases has aroused debate over the past few years and is under active investigation." (PMID 32903550, 2020). "In short, although further work is needed, delineating the pathological role of AIM2 inflammasome will undoubtedly advance the development of oral disease therapy." (PMID 32903550, 2020). "Third, given the close relationship between inflammasome-mediated pyroptosis and infectious diseases or cancer, exploring AIM2/caspase-1/GSDMD axis in oral diseases will be of great importance to the current knowledge." (PMID 32903550, 2020). "In particular, open questions that remain are what inflammatory reactions in oral diseases are AIM2-dependent, NLRP3-dependent, or both." (PMID 32903550, 2020). "Due to its ability to sense dsDNA from various origins, AIM2 is involved in the pathogenesis of many diseases, including inflammatory skin disorders, inflammatory bowel diseases, chronic kidney disease, auto-inflammatory diseases, oral diseases, and cancer." (PMID 41440367, 2025). "AIM2 inflammasome may potentially be a key link between oral diseases and innate immunity." (PMID 32903550, 2020). "In this review, we highlight the current knowledge of the AIM2 inflammasome and its critical role in the pathogenesis of various oral diseases, which might offer future possibilities for disease prevention and targeted therapy utilizing this continued understanding." (PMID 32903550, 2020). "Thus, in this review, we highlight the current knowledge on the AIM2 inflammasome and its critical role in the pathogenesis of various oral diseases, which might offer directions for the next 10 years." (PMID 32903550, 2020). "In addition to NLRP3 being implicated in chronic inflammation and cancer progression, the dsDNA-sensing PRRs, AIM2 and IFI16, have been involved in oral diseases and cancer." (PMID 41440367, 2025).
post-traumatic stress disorder (2 papers, 2020 to 2022). An anxiety disorder precipitated by an experience of intense fear or horror while exposed to a traumatic (especially life-threatening) event. "Methylation of AIM2 locus was previously reported to be related to trauma exposure, post-traumatic stress disorder, and C-reactive protein associations." (PMID 36072791, 2022). "AIM2 methylation has also been associated with C-reactive protein (C-RP) polymorphism and C-RP levels in people with post-traumatic stress disorder (PTSD)." (PMID 33643304, 2020).
prostate diseases (2 papers, 2020 to 2021). "Because our observations implicate a role for the POP3 protein in aging-related prostatic inflammation, further work will be needed to examine the role of androgen-AR/POP3/AIM2 axis in the development of aging-related prostatic diseases." (PMID 33923931, 2021). "NALP1, NALP3, and AIM2 inflammasomes were found important in prostate diseases." (PMID 32486412, 2020).
retinal disease (2 papers, 2025). "In sharp contrast, both RIPK1 and RIPK3 proteins were detected within MCMV-infected of wildtype MAIDS-10 mice, as well as MCMV-infected eyes of MAIDS-10 mice deficient in either NLRP3, NLRP1b, or AIM2, all of which exhibited an atypical pattern of retinal disease." (PMID 41011779, 2025). "In comparison, histopathologic analysis of MCMV-infected eyes of groups of NLRP3−/− MAIDS-10 mice, NLRP1b−/− MAIDS-10, and AIM2−/− MAIDS-10 mice all consistently showed a consistent and similar pattern of atypical retinal disease." (PMID 41011779, 2025). "Importantly, MCMV-infected eyes of MAIDS-10 mice deficient in either caspase-1, GSDMD, or IL-18 all consistently showed a pattern of retinal disease similar, if not identical, to that observed in the present study for MAIDS-10 mice deficient in the NLRP3, NLRP1b, or AIM2 inflammasomes." (PMID 41011779, 2025).